E2F2 (E2F transcription factor 2)
Description:
Transcription activator that binds DNA cooperatively with DP proteins through the E2 recognition site, 5'-TTTC[CG]CGC-3' found in the promoter region of a number of genes whose products are involved in cell cycle regulation or in DNA replication. The DRTF1/E2F complex functions in the control of cell-cycle progression from g1 to s phase. E2F2 binds specifically to RB1 in a cell-cycle dependent manner.
Synonyms: E2F-2
Tractability: PROTAC: ubiquitination databases record sites on it. Other modalities: a drug acting on it is in phase 2 or 3 trials.
Gene: Protein-coding gene on chromosome 1 (23,506,438 to 23,531,233, reverse strand). Ensembl gene ENSG00000007968.
Subcellular location: Nucleus
Pathways (Reactome):
Cellular responses to stimuli: Oncogene Induced Senescence; Oxidative Stress Induced Senescence
Cell Cycle: Cyclin D associated events in G1
Disease: Defective binding of RB1 mutants to E2F1,(E2F2, E2F3)
Gene Ontology:
Molecular function: cis-regulatory region sequence-specific DNA binding; DNA-binding transcription activator activity, RNA polymerase II-specific; protein binding; RNA polymerase II transcription regulatory region sequence-specific DNA binding; sequence-specific DNA binding; sequence-specific double-stranded DNA binding; DNA binding; DNA-binding transcription factor activity; DNA-binding transcription factor activity, RNA polymerase II-specific; RNA polymerase II cis-regulatory region sequence-specific DNA binding; protein dimerization activity
Biological process: negative regulation of sprouting angiogenesis; positive regulation of transcription by RNA polymerase II; regulation of transcription by RNA polymerase II; transcription initiation at RNA polymerase II promoter; regulation of DNA-templated transcription
Cellular component: RNA polymerase II transcription regulator complex; chromatin; nucleoplasm; nucleus; transcription regulator complex
Genetic constraint (gnomAD): Loss-of-function variants: 20 observed, 38.19 expected, observed/expected ratio (o/e) 0.52, 90% interval 0.37 to 0.76. The upper end of that interval is the gene's LOEUF score, 0.76, which puts it in group 3 of 6, group 1 being the genes least tolerant of losing a copy. Missense variants: 466 observed, 542.61 expected, observed/expected ratio (o/e) 0.86, 90% interval 0.8 to 0.93. Synonymous variants: 246 observed, 245.61 expected, observed/expected ratio (o/e) 1, 90% interval 0.9 to 1.11.
Homologues: Orthologues: chimpanzee E2F2 (99% identical), macaque E2F2 (98% identical), pig E2F2 (89% identical), dog E2F2 (88% identical), mouse E2f2 (83% identical), rat E2f2 (82% identical), guinea pig E2F2 (81% identical), rabbit E2F2 (70% identical), Drosophila melanogaster E2f1 (30% identical), Drosophila melanogaster E2f2 (21% identical), Caenorhabditis elegans efl-2 (19% identical), Caenorhabditis elegans efl-3 (19% identical), and 1 more. Paralogues in human: E2F3 (46% identical), E2F1 (38% identical), E2F4 (28% identical), E2F5 (25% identical), E2F6 (25% identical), E2F8 (22% identical), E2F7 (21% identical).
Diseases named in the same sentence as E2F2 in open-access papers:
E2F2 is named in the same sentence as 128 diseases in open-access papers, as found by Europe PMC text mining. Sharing a sentence is not in itself a finding about the gene and the disease. The quoted sentences say what the papers report.
breast carcinoma (61 papers, 2013 to 2025). "Yuwanita reported that E2F2 loss results in increased metastasis in Myc-driven breast cancer through a PTPRD dependent mechanism potentially." (PMID 38807594, 2024). "Consistent with the prediction from the mouse mammary tumor data, human breast cancer with low E2F2 activity contained significantly more copy number variants than those with high E2F2 activity (p < 0.05)." (PMID 33087787, 2020). "In human breast cancer samples, low activation of E2F2 is associated with increased relapse-free survival time." (PMID 32806777, 2020). "Another breast cancer study showed that loss of E2F2 expression significantly reduced tumor metastatic capacity after E2F2 reduction." (PMID 27174918, 2016). "It has been reported that E2F2 mutation and its pathway activation were associated with tumor proliferation and survival of breast cancer patients." (PMID 27174918, 2016). "Taken together, these data indicate that E2F2 loss results in increased metastasis in breast cancer, potentially functioning through a PTPRD dependent mechanism." (PMID 26474282, 2015). "Combining these various criteria, we identified 7 genes that had potential to mediate metastasis by E2F2 loss in Myc induced breast cancer." (PMID 26474282, 2015). "Taken together these findings suggested that E2F2 loss regulated breast cancer metastasis in a subpopulation of human tumors, potentially through a PTPRD signaling axis." (PMID 26474282, 2015). "Our data suggests an additional role for PTPRD in mediating breast cancer metastasis in conjunction with the loss of E2F2." (PMID 26474282, 2015). "Here we demonstrate that loss of E2F2 in Myc induced tumors dramatically increased breast cancer metastasis." (PMID 26474282, 2015). "Accordingly, high E2F2 expression was recently reported to be associated with poor survival of breast cancer patients." (PMID 25202354, 2014). "E2F2 has been linked to tumourigenesis,metastasis and poor overall survival in breast cancer." (PMID 36124841, 2022). "By analyzing gene signatures in The Cancer Genome Atlas, it was identified that increased E2F Transcription Factor 1 (E2F1) and increased E2F Transcription Factor 2 (E2F2), two members of the E2F family, were correlated with a loss of function of Rb in ER+ breast cancers." (PMID 34830174, 2021). "Here, we report our findings regarding the effects of LXR activation on breast cancer transcriptomes, the potential role of E2F2 in mediating the anti-proliferative effects in ER+ breast cancer cells, and association of ligand-responsive gene networks with disease outcomes in breast cancer patients." (PMID 23809258, 2013). "In addition, E2F2 pathway was associated with relapse-free survival time of breast cancer patients." (PMID 30813560, 2019). "Importantly, previous studies have shown that elevated expression of upregulated genes in the E2F1 and E2F2 signature genes are associated with decreased time to distant metastasis free survival in breast cancer patients compared to those with low expression of these genes." (PMID 29617434, 2018). "Of note is the group of genes SP1, MYC, HEY2, E2F1, E2F2, and HES1, which are known to be associated with the KEGG breast cancer functional pathway." (PMID 40724805, 2025). "Some studies have shown that E2F2 can presumably promote tumour development and progression in various types of cancer, including lung adenocarcinoma, breast cancer, ovarian cancer and colorectal cancer." (PMID 37185737, 2023). "E2F2 was a well-established oncogene as it was overexpressed in breast cancer and ovarian cancer and related to advanced phase, high recurrence rate, and disappointing prognosis." (PMID 36245705, 2022).
breast carcinoma (continued). "It is also known that circ_RPPH1/miR-146b-3p/E2F2 axis can promote the progression of breast cancer." (PMID 36551770, 2022). "Previous researches have revealed that elevated E2F2 is significantly correlated with poor prognosis in hepatocellular carcinoma 40, ovarian cancer 14 and breast cancer." (PMID 35069909, 2022). "It has been reported that E2F2 plays a carcinogenic role in liver cancer and breast cancer, while in prostate cancer, E2F2 inhibits tumor cell proliferation by targeting micorRNA." (PMID 34091441, 2021). "The data presented here, combined with the previously established literature, show key roles of E2F1 and E2F2 as contributing factors in the genomic instability seen in breast cancer." (PMID 33087787, 2020). "In human breast cancer E2F2, status was also correlated with a patient’s response to PARP inhibition therapy." (PMID 33087787, 2020). "Here we present an integrative bioinformatic and high throughput drug screening study to define the role of E2F2 in maintaining genomic integrity in breast cancer." (PMID 33087787, 2020). "Consistent with the mouse data we identified E2F2 high HER2 positive breast cancer to have worse overall survival as determined by log rank P-value across the KMplot dataset." (PMID 33087787, 2020). "After predicting the E2F2 activity level across all breast cancer datasets we identified differentially lethal compounds between E2F2 low cell lines and E2F2 high cell lines." (PMID 33087787, 2020). "In a previous study, we demonstrated that E2F1, E2F2, and E2F3a are highly deregulated in breast cancer and their individual overexpression induced CA and CIN in MCF10A mammary epithelial cells." (PMID 29100415, 2017). "We established a gene expression signature of Rb loss-of-function (RBsig) by identifying genes correlated with E2F1 and E2F2 expression in breast cancers within The Cancer Genome Atlas." (PMID 27634906, 2016). "For the predicted TF signaling pathways, certain signaling pathways have been detected in other types of cancer; for instance, ZEB1 regulates hsa-miR-34a in lung cancer and hsa-miR-21 targets E2F2 in breast cancer." (PMID 25289101, 2014). "Similar results were obtained with MMTV-Myc transgenic mice, in which E2F2 knockout delayed latency and reduced the incidence of Myc-driven mammary tumors." (PMID 25202354, 2014). "Response of E2F target genes were validated by real-time PCR, and the posited role of E2F2 in breast cancer cell proliferation was tested by RNA interference experiments." (PMID 23809258, 2013). "However, low E2F2 expression leaded PARP inhibitor therapy resistance in breast cancer, this entirely different result indicated the heterogeneity between malignancies and drug responses." (PMID 39999286, 2025). "Although direct evidence for its ligand-dependent coregulator function with ESR1 in this disease remains limited, studies in ESR1-positive breast cancers have shown that ZMIZ1 participates in the ESR1 chromatin-bound complex to enhance the expression of cell cycle regulators such as E2F2." (PMID 41321319, 2025). "Furthermore, estradiol (E2) induced the upregulation of miR-98 and other miRNAs in MCF-7 breast cancer cells, which resulted in a decrease in c-Myc and E2F2 protein levels, demonstrating miR-98’s role in the E2 response pathway in breast cancer scenarios." (PMID 38872210, 2024). "Additionally, H3K4me3 demethylation has been shown to affect AURKB and E2F2 transcription levels in breast cancer tumors and is correlated with poor clinical outcomes." (PMID 36982384, 2023). "The D-Arg PEP targeting activator family members of transcription factor E2F— namely, E2F-1, E2F-2, and E2F-3a—showed a synergistic anti-cancer effect when used in combination with chemotherapeutic drug cisplatin against the prostate cancer, breast cancer, and lymphoma cell lines." (PMID 33652640, 2021).
breast carcinoma (continued). "Moreover, E2F2 has been reported to promote tumor progression in many other human cancers, including breast cancer, ovarian cancer, lung cancer, and glioma." (PMID 34295816, 2021). "Finally, this data was compared to human datasets to identify conserved roles of E2F2 in human breast cancer through the TCGA breast cancer, Cancer Cell Line Encyclopedia, and CancerRx datasets." (PMID 33087787, 2020). "In conclusion, the overexpression of AURKB, GINS2, MCM10, UHRF1, POLE2, SPC24, and E2F2 in HER2-positive breast cancer patients with ALR showed that these hub genes could be potential prognostic biomarkers in such patients." (PMID 33013420, 2020). "While we have identified a potential role for E2F2 associated instability in mouse tumors, this role has not previously been examined in human breast cancer." (PMID 33087787, 2020). "In order to establish a system where we could assess the effects of PTPRD knockdown, we began by examining whether the mouse effects of E2F2 translated to human breast cancer." (PMID 26474282, 2015). "This increase of PTPRD could then lead to increased lung metastasis, a role for PTPRD and E2F2 that is unique to a subpopulation of breast cancer." (PMID 26474282, 2015). "To determine the role of E2F2 in breast cancer cell proliferation, we carried out RNA interference experiments in MCF-7 and T-47D (ER+) and MDA-MB-231 (ER-) cells and measured the effects of E2F2 knockdown, mimicking the effects of LXR ligand treatment, on cell numbers over a 72-hour period." (PMID 23809258, 2013). "In addition, E2F2 is related to breast cancer stem cells (BCSCs)." (PMID 38807594, 2024). "Moreover, circ_RPPH1/miR-146b-3p/E2F2 axis could promote the progression of breast cancer and circCUL2/miR-214-5p/E2F2 axis-suppressed retinoblastoma cells." (PMID 37047293, 2023). "As for E2F2, in addition to its putative canonical role in cell cycle and cell proliferation, its role in tumorigenesis has been also documented by several groups in several types of cancers, including ovarian cancer, breast cancer, colorectal cancer, etc 17-21." (PMID 35844795, 2022). "E2F2 may act through PTPRD to increase metastasis in the MMTV-Myc model of breast cancer." (PMID 26474282, 2015). "However, knockdown of E2F2 in breast cancer cell lines only blocked proliferation in ER+ cell lines which suggests that mechanisms of cell proliferation inhibition by LXRs may be diverse in nature." (PMID 25184494, 2014). "In breast cancer, ZMIZ1 enhances ESR1-dependent expression of E2F2, correlating with poor patient outcomes." (PMID 41321319, 2025). "Therefore, E2F2 may be a potential target for breast cancer therapy." (PMID 38807594, 2024). "E2F1 and c-Myc are overexpressed in basal breast cancers from NHB women, FoxM1 in Her2 + breast cancers from NHW women, FoxM1, E2F1 and E2F2 in Luminal A breast cancers from NHB women." (PMID 36494865, 2022). "In total, we describe a role of E2F2 in repair and maintenance of genome integrity in both MMTV-Neu mouse model mammary tumors as well as in human breast cancer patients." (PMID 33087787, 2020). "Consistently, BIRC5, E2F2, FOXM, and MCM5, showed higher expression in breast cancer tissues than in normal tissues, according to the immunohistochemical assessment from HPA database." (PMID 31579605, 2019). "Present study revealed significant down-regulation of cell cycle and DNA damage response genes, including E2F1, E2F2, RAD51, and CCNB1 in breast cancer cells treated with palbociclib." (PMID 31548560, 2019). "RB1 has been shown to inhibit the E2F1 and E2F2 transcriptional factors; therefore, the allelic deletion of RB1 that was observed in 85% of breast cancer patients in our study is likely to lead to the activation of E2F1 and E2F2." (PMID 26799285, 2016). "Specifically in breast cancer, E2F1 expression has been shown to be reduced in primary and metastatic breast carcinoma and deletion of the E2F2 chromosomal region was also observed." (PMID 26474282, 2015).
breast carcinoma (continued). "Knockdown of E2F2 expression, similar to LXR ligand treatment, resulted in a significant disruption of estrogen receptor positive breast cancer cell proliferation." (PMID 23809258, 2013). "In the breast cancer cell study, interaction between ESR1 and ZMIZ1 to regulate cell cycle progression genes was hypothesized, with demonstrated interactions at the E2F2 gene promoter." (PMID 41321316, 2025). "Our group pioneered the study of SGO1 in breast cancer in general by demonstrating, using cBIOPORTAL, that the overexpression of SGO1 in breast tumors correlates with the overexpression of the E2F transcriptional activators E2F1, E2F2, and E2F3." (PMID 37122033, 2023). "Some studies demonstrate increased E2F2 gene expression in cancers such as ovarian cancer, non-small cell lung cancer, hepatocellular carcinoma and breast cancer." (PMID 36551770, 2022). "Although 1222 target genes of miR-10b-5p were predicted and 48 significantly negatively correlated genes were obtained, only 5 overlapped genes, BIRC5, E2F2, KIF2C, FOXM1, and MCM5, were considered as potential key targets of miR-10b-5p in breast cancer for further analysis." (PMID 31579605, 2019). "Using cBioPortal analysis of the TCGA database, we next addressed whether individual genes co-occurred in breast cancers and found significant correlations between E2F1 overexpression and E2F2, E2F1 overexpression and E2F3, and E2F2 overexpression and E2F3." (PMID 29100415, 2017). "These known targets included CEBPα, STK40, and E2F2 which had been shown to be downregulated at mRNA level by miR-31-H in ovarian cancer cells and Frizzled3 (Fzd3) and MMP16 which were repressed at the protein level by miR-31 in MDA-MB-231 breast cancer cells." (PMID 23472152, 2013). "Inhibition of E2F2 could reduce the proportion of CD24-/CD44+ cells and the expression levels of SOX2 and OCT4, thus inhibiting the self-renewal, proliferation and invasion ability of BCSCs and inhibiting the growth of breast cancer tumors." (PMID 38807594, 2024). "Indeed, E2F2/5/8 have been shown to be novel biomarkers for prognosis for ovarian cancer, E2F1/2/5/8 for lung cancer, and multiple members of E2F for gastric and breast cancer." (PMID 33329696, 2020). "Knockdown of E2F2 expression by RNA interference disrupted ER+ breast cancer cell proliferation, indicating that downregulation of E2F2 expression by ligand activation of LXRs is a potential mechanism of action for LXR ligands and their anti-proliferative effects in ER+ breast cancer cells." (PMID 23809258, 2013). "Our analysis of a breast cancer dataset finds that the positive feedback loops across 7 genes, AR, ESR1, MYC, E2F2, PGR, BCL2 and CCND1 are conserved across the basal/triple negative subtypes in multiple datasets that could potentially explain the aggressive nature of this cancer subtype." (PMID 23368093, 2013). "Upregulation of the activating E2F genes was also found in basal versus not-basal breast cancer: E2F1 (FC = 2.01, P = 8.72E-06), E2F2 (FC = 1.98, P = 2.97E-07), and E2F3 (FC = 1.95, P = 8.13E-17)." (PMID 25161863, 2014). "Similarly to the patterns of expression of mitotic kinases in breast cancers that do not fall under traditional classification (or that failed to classify) FOXM1, E2F1, E2F2, E2F3, and c-Myc are overexpressed in that subtype." (PMID 36494865, 2022). "It is important to note that E2F2 is repressed significantly in BxPC-3 cells and not in the other two PDAC cells, and this observation suggests that mechanisms discovered in breast cancer cells may not necessarily be involved in pancreatic cancer cells." (PMID 25184494, 2014). "In both cases, broadlyaccepted breast cancer drivers such as BRCA1 and ESR1 are central nodes in the network.The network analysis has revealed severalinfluential DCDs that are not curated CGC genes yet, for example E2F2 and THRA fromsingle-cell, and SIN3A from bulk data." (PMID 36124841, 2022).